CASP9 (caspase 9)
Diseases named in the same sentence as CASP9 in open-access papers (continued):
Sharing a sentence is not in itself a finding about the gene and the disease.
glioma (continued). "As we observed that HATi II induced apoptosis in glioma cells, we examined the cleavage of PARP, caspase-9 and caspase-3 by Western blotting." (PMID 25523932, 2014). "We observed that 10 μM SAHA promoted the cleavage of both Caspase 9 and Caspase 3, whereas 10 mM VPA had a weaker effect in all glioma cell lines." (PMID 25275596, 2014). "Stronger apoptogenic effect of TMZ-Se was validated by the increased amounts of cleaved caspase-3, caspase-9 and PARP, and the decreased amounts of the anti-apoptotic protein, survivin, in the TMZ-Se-treated glioma cells, as determined by western blot." (PMID 22496897, 2012). "Finally, combined with Multivariate Cox regression analyses, four PRGs (CASP4, CASP9, GSDMC, IL1A) were identified as prognostic biomarkers for glioma patients." (PMID 35547808, 2022). "In addition, we explored the proteins express by CASP4, CASP9, and GSDMC in glioma patients through the Human Protein Atlas database, and CASP4, CASP9 exhibited higher staining intensity in glioma than normal brain tissues." (PMID 35547808, 2022). "We also observed that in both glioma cell lines, TSAIII induces cell death and mitochondrial dysfunction, consistent with observed increases in the protein expression of cleaved-caspase-3, cleaved-caspase-9, cleaved-PARP, cytochrome c, and Mcl-1." (PMID 36611961, 2022). "As a tumor suppressor in glioma, lncRNA TUG1 could activate caspase-3 and caspase-9 dependent pathways and suppress Bcl-2 dependent anti-apoptosis pathway." (PMID 28548946, 2017). "In our study, the expressions of cyclinD1, ki67 and XIAP were obviously reduced by the overexpression of KNG1; while the expressions of caspase-3 and caspase-9 were increased, suggesting the up-regulation of KNG1 could exert pro-apoptotic property in glioma cells." (PMID 30068373, 2018). "Herein, ADM knockdown or TMZ treatment induced caspase 3 and caspase 9 cleavage, as well as mitochondrial membrane potential impairment, suggesting that mitochondrial function might also be involved in ADM knockdown enhancing glioma cell sensitivity to TMZ treatment." (PMID 36183123, 2022).
hepatocellular carcinoma (61 papers, 2011 to 2025). A malignant tumor that arises from hepatocytes. "The occurrence and development of hepatocellular carcinoma induced by miR-155 is closely associated with the expression of Caspase3, Caspase-9, and PTEN." (PMID 32411077, 2020). "In another study, berbamine applied to SMMC7721 hepatocellular carcinoma cells caused cell cycle arrest in the G0/G1 phase, induced a loss of mitochondrial membrane potential (Δψm) and induced the activation of caspase-3 and caspase-9." (PMID 32093423, 2020). "Cnt treatment modulated mitochondria-dependent apoptosis pathways in hepatoma cells by inducing the upregulation of caspase-9 and caspase-3." (PMID 40290068, 2025). "Previous study shows that TGF-β signaling pathway can regulate cell apoptosis by upregulating BIM, BMF, DAPK expression, and TAT induces hepatoma cell apoptosis by activating caspase-9." (PMID 38769521, 2024). "Simultaneous treatment with Sora and Cur also increased the expression of cleaved caspase-3, cleaved caspase-9, and Bcl-xL in the HepG2 and Hep3b hepatocellular cancer cell lines." (PMID 37365571, 2023). "Being consistent with the previous finding in hepatocellular carcinoma, the intrinsic apoptotic pathway (caspase 9) was involved in this dovitinib-mediated tumor cell death." (PMID 31485222, 2019). "This is in line with previous reports that showed that JQ1 activated Caspase 9 in established cancer cell lines, including hepatocellular carcinoma and glioblastoma cells." (PMID 30333915, 2018). "Although esculetin (a coumarin compound) blocked the cell cycle at the S subphase, it induced apoptosis in the SMMC-7721 human hepatocellular carcinoma cell line with a significant elevation in caspase-3 and caspase-9 activities." (PMID 28472978, 2017). "In hepatocellular carcinoma cells, TM strongly enhanced the activation of caspase-3, caspase-8, and caspase-9." (PMID 28018916, 2016). "Findings of a recent study showed that berberine extracts promoted autophagy by activating beclin 1 expression and activated caspase-9 to induce apoptosis in hepatoma cells." (PMID 24676394, 2014). "The present study showed that MTX induces increases in H2O2 levels and caspase-9/-3 activation leading to cell death in hepatocellular carcinoma Hep3B cells." (PMID 24969544, 2014). "Some studies have shown that MTX-induced apoptosis is mediated by the caspase-9/-3 cascade pathway in choriocarcinoma, breast cancer, oral squamous carcinoma and hepatoma cells." (PMID 24969544, 2014). "Taking together, our research explored that Smad2/3/4 complex could undergo LLPS and binds to TAT gene promotor site to upregulate TAT expression, which can active caspase-9 to induce hepatoma cell apoptosis." (PMID 38769521, 2024). "Western-Blot and Flow cytometry assays results suggested that Smad2/3/4 complex could active caspase-9 to improve hepatoma cell apoptosis through TAT." (PMID 38769521, 2024). "To generalise our findings, we treated five commonly used cancer cell lines of colorectal (DLD1, HCT116 and SW480), breast (MDA231) and hepatocellular carcinoma (SNU387) origin with oxaliplatin to activate caspase-9, or death-receptor ligand TRAIL to activate caspase-8,-initiated apoptosis." (PMID 38272916, 2024). "We discovered that overexpressed TAT could increase the expression of cleaved caspase-9, but knocking down Smad2 could decrease cleaved caspase-9 level in hepatoma cell lines, so as Smad3 and Smad4." (PMID 38769521, 2024). "Western blot results showed that, all three members could increase the expression of cleaved caspase-9 in hepatoma cell lines." (PMID 38769521, 2024). "Smad2/3/4 activated caspase-9 through regulating TAT to induce hepatoma cell apoptosis." (PMID 38769521, 2024). "All these results suggest that Smad2/3/4 complex could active caspase-9 and induce hepatoma cell apoptosis through regulating TAT." (PMID 38769521, 2024).
hepatocellular carcinoma (continued). "Interestingly, ALO also induces the activation of caspase-9 and caspase-3 in osteosarcoma and hepatocellular carcinoma cells." (PMID 34895234, 2021). "In a previous study, UDCA could also increase caspase-3, caspase-8 and caspase-9 activities to induce apoptosis in HepG2 hepatocellular carcinoma cells." (PMID 25951128, 2015). "In addition, therapeutic-dose treatment induced an increase in the H2O2 level, activated the caspase-9/-3 cascade, and induced cell apoptosis of hepatoma cells." (PMID 24682227, 2014). "Moreover, it was demonstrated that ginsenoside (Rh2) induces apoptosis of human hepatoma cells via Bax/Bak and caspase-9/caspase-8 activation." (PMID 24981420, 2014). "Probably, Smad2/3/4 complex could active caspase-9 through TAT to induce hepatoma cell apoptosis." (PMID 38769521, 2024). "In addition, we found that Smad2/3/4 complex could active caspase-9 to induce hepatoma cell apoptosis through regulating TAT." (PMID 38769521, 2024). "Looking at hepatocellular carcinoma (HCC), propofol also efficiently inhibited the growth of HCC cells and activated both caspase-8 and caspase-9, suggesting that both intrinsic and extrinsic pathways induce apoptosis." (PMID 36143832, 2022). "Vexosomes were also used to deliver inducible caspase 9 (iCasp9) in Huh7 hepatic cancer cells and in hepatocellular carcinoma (HCC) xenograft mouse models." (PMID 35047931, 2021). "We have recently demonstrated the potential of a AAV2-mediated inducible caspase 9 (iCasp9) gene delivery in a hepatocellular carcinoma (HCC) model." (PMID 32258213, 2020). "In hepatocellular carcinoma (HCC), ETHE1 is overexpressed, where it is associated with inhibition of caspase 9 activation, suppressing DNA-damage induced apoptosis by binding to the RelA p65 subunit of NFkB, and increasing its export from the nucleus." (PMID 31258845, 2019). "In addition, activation of the caspase-9/-3 cascade is also found in APAP-treated hepatoma cells." (PMID 26096646, 2015). "Western blot results showed that Smad2/3/4 complex would active caspase-9 through TAT, which uncovered the mechanism of Smad2/3/4 complex inducing hepatoma cell apoptosis." (PMID 38769521, 2024). "In hepatocellular carcinoma, PCSK9 was found to promote cell growth by inhibiting cell apoptosis via the involvement of the Bax/Bcl-2/Caspase-9/Caspase-3 pathway." (PMID 38611089, 2024). "demonstrate that AAV6 serotype-based vexosomes, containing an inducible caspase 9 gene, are cytotoxic in the presence of a pro-drug AP20187 and have a significant therapeutic potential for suicide gene therapy in hepatocellular carcinoma." (PMID 32258213, 2020). "Furthermore, it has been shown that TGFβ1 up-regulates miR-155 in hepatocellular carcinoma cells, thus promoting epithelium-to-mesenchyme transition, invasion and metastasis, and that miR-155 plays a role in mediating TGFβ1-induced podocyte injury via nephrin, desmin and caspase-9." (PMID 29987196, 2018). "Additionally, it was found to induce apoptosis in hepatocellular carcinoma (HCC) cells (HepG2) by promoting the release of cytochrome c into the cytoplasm, thereby activating caspase-8, caspase-9, and caspase-3." (PMID 39770441, 2024). "In hepatoma HepG2 cells, TSAIII treatment is reported to activate cleaved-caspase-3, caspase-8, and caspase-9, increase the expression of Mcl-1 and Bcl-2, and induce the release of cytochrome C, suggesting that TSAIII induces caspase-dependent and mitochondrial-mediated apoptosis." (PMID 36611961, 2022). "It was found that protopine treatment enhanced the activities of caspase-3 and caspase-9 but not caspase-8 in a dose-dependent manner in liver carcinoma cells." (PMID 34315493, 2021). "Similarly, studies conducted in the human hepatoma (hepatocellular carcinoma) cell line Huh7 showed that part of the early response to TGF-β was an increase in the activity of caspase-8, followed by the activation of caspase-9 and caspase-3." (PMID 38672279, 2024).
hepatocellular carcinoma (continued). "OA activates apoptosis in the hepatocellular carcinoma (HCC) cells SMMC-7721 and BEL-7404 by altering the Bax/Bcl2 balance, inducing the release of cytochrome-c and activating caspase-9 and caspase-3." (PMID 39064870, 2024). "Gal-9 can induce apoptosis of hepatocellular carcinoma (HCC), hence inhibiting tumor growth, possibly mediated via the miR-1246-DYRK1A-caspase-9 axis." (PMID 36555198, 2022). "Furthermore, JS-K increased Bax-to-Bcl-2 ratio, released Cyt c from mitochondria and increased the activities of cleaved-caspase-9/3.Therefore, PP2A activation mechanism contributes to JS-K induced caspase-dependent apoptosis in human hepatocellular carcinoma cells." (PMID 29986744, 2018). "Moreover, celecoxib was found to inhibit the growth of hepatocellular carcinoma cells by activating retinoblastoma protein (pRb) through its hypophosphorylation, thus repressing the DP1/E2F1 complex, and inducing apoptosis through the activation of caspase-3 and caspase-9." (PMID 34065773, 2021).
leukemia (61 papers, 2002 to 2025). A malignant (clonal) hematologic disorder, involving hematopoietic stem cells and characterized by the presence of primitive or atypical myeloid or lymphoid cells in the bone marrow and the blood. "Polymorphisms in several introns and promoter regions of CASP9 are associated with the incidence and progression of lung, breast, liver, esophageal, leukemia, and other cancers." (PMID 36552744, 2022). "Doxorubicin and etoposide when used in combination with each polyphenol caused a synergistic increase in caspase 9 activity (P<0.05) in all leukaemia cell lines." (PMID 27551472, 2015). "We reported previously that NO-mediated apoptosis in human leukaemia cells is associated with mitochondrial damage (i.e., a degradation of major mitochondrial lipid cardiolipin and cytochrome c release into the cytosol) followed by an activation of caspase-9 and caspase-3." (PMID 11875749, 2002). "Another study shows that It can induce apoptosis in HL-60 leukemia cells by activation of caspase-3 and caspase-9 enzymes." (PMID 38706463, 2024). "Another study demonstrated TSAIII-induced apoptosis of human leukemia HL-60 cells via cleaved-caspase-3, caspase-8, caspase-9, and PARP in a dose- and time-dependent manner." (PMID 36611961, 2022). "Our results showed that the apoptosis proteins, cleaved caspase 3, cleaved caspase 9 and Bax, were aberrantly over-expressed after knocking down IL-1β in leukemia cells by siRNA, while Bcl-2 onco-protein was down-regulated." (PMID 34211462, 2021). "In contrast, caspase-9-induced leukemia apoptosis timed with T cell infusions and FGK45 improved antigen presentation and alloreactive T cell activation." (PMID 32839441, 2020). "The dibromotyrosine derivative (1′R,5′S,6′S)-2-(3′,5′-dibromo-1′,6′- dihydroxy-4′-oxocyclohex-2′-enyl) acetonitrile, isolated from Pseudoceratina sp., exhibited apoptotic activity by the activation of caspase-9 in leukemia K562 cells." (PMID 30795557, 2019). "This resulted in a synergistic increase in caspase 8 and 9 when combined with quercetin or apigenin, and caspase 9 when combined with emodin or rhein in each investigated leukaemia cell line." (PMID 31360305, 2019). "The incubation with AD0157 at concentrations of 1 μM or higher (5 and 10 μM), significantly enhanced the activities of the initiator caspase-8 and caspase-9, and the effector caspases-3/-7 in a dose-dependent manner in the different leukemia cells." (PMID 29163182, 2017). "Vitexin is suggested to serve as a therapeutic agent for the treatment of human leukemia, as it promoted the expression of cleaved caspase-3 and cleaved caspase-9 in leukemia cells and simultaneously reduced Bcl-2 expression and therefore induced apoptosis." (PMID 27630565, 2016). "The present study investigated the proapoptotic activity of quercetin by activating caspase-3 and caspase-9, which was consistent with the studies on leukemia cells." (PMID 27329589, 2016). "Embelin treatment of the leukemia cell line HL 60 caused a reduction in XIAP protein levels and increased caspase 3 and caspase 9 cleavage." (PMID 24603802, 2014). "Several studies indicated that decreasing Caspase-9 transcription and translation are detected in head and neck squamous cell carcinoma, and leukemia." (PMID 22974165, 2012). "Induction of apoptosis through the intrinsic, mitochondrial pathway was further investigated in leukemia cells via assessment of cleavage/activation of caspase-3, caspase-9, and PARP." (PMID 21826188, 2012). "Caspase 9 cleavage was observed in nelfinavir-treated leukemia cells by Western blot analysis, but the bands were rather faint." (PMID 20105315, 2010). "Previous studies have shown that vitexin treatment leads to apoptosis, a reduction in mitochondrial membrane potential and Bcl-2 protein expression and elevated Caspase-3 and Caspase-9 protein expression in human non-small-cell lung cancer A549 cells and human leukemia K-562 cells." (PMID 35281458, 2022).
leukemia (continued). "A step forward has come with the introduction of inducible caspase-9 (iC9) protein, fused to human caspase-9 and to modified FK506-binding protein, which has overcome several concerns associated with HSV-TK and has shown an effect against GVHD in leukemia." (PMID 35053386, 2022). "These coumadin hybrids can up-regulate the expression of caspase-3 proteins in HCC cell lines and caspase-3 and caspase-9 proteins in leukemia cell lines, and down-regulate the expression of Bcl-2 and the up-regulation of Bax protein expression levels in HCC and leukemia cell lines." (PMID 33344242, 2020). "The activation of caspases is essential for apoptosis; we tested the caspase-3 activity and detected caspase-3 activation, and during the blocking of caspase-3, caspase -8, and caspase -9, cell death was inhibited, indicating apoptosis in the leukemia cell line." (PMID 32587616, 2020). "To further demonstrate whether LEE011 causes apoptosis in leukemia cells, we assessed the expression and cleavage of the apoptosis markers PARP, caspase-3 and caspase-9 by western blot." (PMID 28286417, 2017). "Considering that caspase-9 is the initiator caspase responsible for the mitochondrial apoptosis, we analyzed several other features of this pathway in order to define the mechanism of hydralazine-induced apoptosis in leukemia T cell lines." (PMID 26942461, 2016). "Also, morin promoted ROS and Ca2+ productions, disruptions of mitochondria membrane potential and activated caspase-3 and caspase-9, leading to apoptosis in human leukemia HL-60 cells." (PMID 25561222, 2014). "Therefore, MJ-29-enhanced apoptosis in murine leukemia WEHI-3 cells was carried out mainly by the activations of caspase-9 and caspase-3-mediated mitochondrial signaling pathways." (PMID 22662126, 2012). "However, it could also be secondary signal to caspase-9/-3-linked cleavage, as reported in PUVA-induced apoptosis of T leukemia cells." (PMID 23685456, 2013). "Also, GRh2 is considered a chemotherapeutic agent for leukemia therapy by inducing apoptosis through the mitochondrial pathway including mitochondrial depolarization, cytochrome complex release, and activation of caspase-9 and caspase-3 in acute leukemia cells." (PMID 38706463, 2024). "Apigenin, has previously been shown to induce apoptosis in leukaemia cells (HL60, THP-1, U937) via mitochondrial-dependent mechanisms, with the release of cytochrome c to the cytosol and the activation of caspase-9 and -351–54." (PMID 35614109, 2022). "In leukemia cells (NALM6), quercetin was found to bring about mitochondrial pathway of apoptosis by increasing cytochrome c, caspase 9 and depolarization of mitochondrial membrane potential." (PMID 31366565, 2019). "Older studies of our group observed CASP9 and CASP8 activation after viscum treatment in different leukaemia cell lines." (PMID 28061770, 2017). "Furthermore, isogarcinol, isoxanthochymol, and guttiferone E were shown to strongly induce apoptosis in the leukemia cell line CCRF-CEM through activation of caspase-3/caspase-7, caspase-8, and caspase-9." (PMID 36865482, 2023). "The absence of caspase-9 readily protected the leukemia Δ9 Jurkat cells from Morniga-G-induced cell death." (PMID 30626136, 2019). "In contrast, decreased expression of caspase-9 did not significantly suppress sTRAIL:FeSOD-induced apoptosis in the leukemia cells, suggesting the apoptosis to be caspase-9-independent." (PMID 21418589, 2011).
leukemia (continued). "Results showed that A14 treatment could enhance cleaved caspase-3 and cleaved caspase-9 in Jurkat cells and THP-1 cells along with inducing the upregulation of caspase-3 downstream, thereby cutting substrate cleaved PARP compared to the control group in both leukemia cells, leading to PARP cutting." (PMID 36510253, 2022). "There existed no obvious difference in Nrf2 expression in leukemia cells treated with MK-2206, but the protein levels of p-AKT and OGG1 decreased significantly, whereas Cleaved-caspase 9 increased significantly." (PMID 36528059, 2022).